TCP11L2 (t-complex 11 like 2)
Description:
Promotes the migration of muscle-derived satellite cells (MDSCs) during differentiation throught interaction with FMNL2 and therefore may participate in microfilament assembly.
Synonyms: MGC40368
Tractability: PROTAC: ubiquitination databases record sites on it; its protein half-life has been measured.
Gene: Protein-coding gene on chromosome 12 (106,301,929 to 106,347,609, forward strand). Ensembl gene ENSG00000166046.
Subcellular location: Cytoplasm, cytoskeleton
Subcellular location (Human Protein Atlas): Nuclear speckles
Gene Ontology:
Molecular function: protein binding
Biological process: muscle cell migration; signal transduction
Cellular component: nuclear speck; cytoplasm; cytoskeleton
Genetic constraint (gnomAD): Loss-of-function variants: 38 observed, 48.33 expected, observed/expected ratio (o/e) 0.79, 90% interval 0.61 to 1.03. The upper end of that interval is the gene's LOEUF score, 1.03, which puts it in group 4 of 6, group 1 being the genes least tolerant of losing a copy. Missense variants: 559 observed, 585.38 expected, observed/expected ratio (o/e) 0.95, 90% interval 0.89 to 1.02. Synonymous variants: 171 observed, 209.86 expected, observed/expected ratio (o/e) 0.81, 90% interval 0.72 to 0.93.
Homologues: Orthologues: chimpanzee TCP11L2 (99% identical), macaque TCP11L2 (97% identical), pig TCP11L2 (92% identical), dog TCP11L2 (92% identical), rat Tcp11l2 (79% identical), mouse Tcp11l2 (78% identical), guinea pig TCP11L2 (75% identical), tropical clawed frog tcp11l2 (58% identical), zebrafish tcp11l2 (53% identical), Drosophila melanogaster CG16721 (30% identical), Caenorhabditis elegans M05D6.2 (24% identical). Paralogues in human: TCP11L1 (42% identical), TCP11 (36% identical), TCP11X1 (34% identical), TCP11X2 (34% identical).
Diseases named in the same sentence as TCP11L2 in open-access papers:
TCP11L2 is named in the same sentence as 6 diseases in open-access papers, as found by Europe PMC text mining. Sharing a sentence is not in itself a finding about the gene and the disease. The quoted sentences say what the papers report.
cancer (1 paper, 2025). A tumor composed of atypical neoplastic, often pleomorphic cells that invade other tissues. "In the LUSC group, we can get a similar conclusion, in addition, DPP4, PARP11, and TCP11L2 were found to be positively correlation with the cancer-associated fibroblasts (CAFs) and endothelial cells." (PMID 39949782, 2025).
tumor (1 paper, 2025). "Additionally, in LUAD, TCP11L2 was the only protein decreased in the tumor samples, and in LUSC, CAB39, DEPDC1B, DPP4, PDPK1, and POLD4 were significantly down-regulated." (PMID 39949782, 2025). "Among them, the expression of TIPRAP, WSCD1, TCP11L2, DPP4, CAB39 and PDPK1 were down-regulated, while PARP1, DEPDC1B, CKAP2, ORMDL2, MRPL44, POLD4 and TMEM187 were increased in tumor group." (PMID 39949782, 2025).
TCP11L2 also shares sentences with these, for which no sentence is quoted: esophageal cancer (1 paper); gastric cancer (1); liver cancer (1); ovarian carcinoma (1).